SOD1 (superoxide dismutase 1)
Diseases named in the same sentence as SOD1 in open-access papers (continued):
Sharing a sentence is not in itself a finding about the gene and the disease.
tumor (continued). "Furthermore, immunohistochemical staining results show a significantly darker brown staining SOD1 in cancerous than adjacent tissues; with SOD1 expression was upregulated in 62.2% (122/196) of tumor tissues but only in 12.2% (22/196) of normal tissue samples (p < 0.05)." (PMID 32391354, 2020). "Therefore FPP® anti-tumor effect was consistent with both the decrease of hydroxyl radicals (the most dangerous among free radicals) levels and the increases of superoxide-dismutase (SOD-1) and glutathione (GSH) antioxidants blood levels." (PMID 30669508, 2019). "We further show that three chemicals predicted to functionally substitute for SOD1 silencing also induce preferential killing within BLM- and CHEK2-deficient cells in short (5-day), moderate (14-day) and long-term (28-days) assays in both 2D culture and 3D tumor models." (PMID 26318585, 2015). "Elevated SOD1 and SOD2 levels often promote oncogenic signalling and tumour survival, whereas SOD3 exhibits context-dependent roles, balancing tumour suppression and progression." (PMID 41799710, 2026). "TM also inhibits copper-dependent enzymes, such as superoxide dismutase (SOD1) and lysyl oxidase (LOX), which play crucial roles in regulating oxidative stress and remodeling the extracellular matrix—key processes in tumor development and metastasis." (PMID 40406488, 2025). "The nuclear enrichment of SOD1 is crucial for the proliferation of NSCLC cells, a fact corroborated by SOD1 inducible knockout studies in KRAS‐driven NSCLC mouse models, which significantly diminished the tumor burden in both in vivo and in vitro settings." (PMID 41498040, 2025). "For example, while cytosolic and mitochondrial superoxide dismutase (SOD1 and SOD2) were more abundant in tumor tissue (especially the mitochondrial isoform SOD2), SOD3, the excreted isoform, was significantly more abundant in healthy tissue." (PMID 40461450, 2025). "In NSCLC, SOD1 supports KRAS-driven tumor growth, and its inhibition—genetically or by the SOD1-targeting agent ATN-224—reduces tumor burden and increases oxidative stress, with minimal toxicity in normal tissues." (PMID 40867898, 2025). "SOD1 inhibitors, including ATN-224 and disulfiram, selectively enhance oxidative stress in tumor cells and are currently being tested in clinical trials." (PMID 40867898, 2025). "To investigate the role of CBPRS in the tumour microenvironment (TME) at the single-cell transcriptome level, we analysed the expression patterns of SOD1, MUC2, FKBP4, LOXL2, GPC1 and SNAI3 in different cell types." (PMID 38577594, 2024). "We analyzed the effect of SYF treatment on the protein expressions of VEGFR2, PPARγ, and SOD1 in TNBC cells and tumor tissues." (PMID 38516703, 2024). "To determine if reducing ROS could preserve muscle morphology, we overexpressed ROS scavengers Catalase (Cat) and superoxide dismutase (Sod1), or antioxidative enzyme glutathione peroxidase 1 (GPx1, previously validated in), specifically in the muscles of tumour-bearing animals (QRasV12scribRNAi)." (PMID 38429578, 2024). "We analysed the changes in antioxidant (SOD1, SOD2, CAT, GPX1, HIF-1α, and NRF2) and anti-inflammatory nuclear factor kappa B (NF-κB) gene expression in tumour-bearing mice." (PMID 39506978, 2024). "This innovative approach allowed us to achieve robust anti-tumor effects, even in chemotherapy-resistant CRC models with high SOD1 expression." (PMID 37742011, 2023). "Both SOD1 and SOD2 protect against spontaneous tumorigenesis, and although they have been described as tumor suppressors, they can also be upregulated during tumorigenesis." (PMID 37107276, 2023). "Aiming to study the levels of known Nrf2 target genes in tumor and normal samples, we measured the total GSH levels and enzymatic activity of SOD1, NQO1, and GST levels in eleven primary tumors and adjacent normal tissues." (PMID 35945195, 2022).
tumor (continued). "It is shown that CLEC7A, VCAN, and KYNU were significantly upregulated in monocytes, BIRC3 and SOD1 were mainly distributed in T cells, CCL20 was highly expressed in tumor cells, and CD69 was highly expressed in B cells." (PMID 35480896, 2022). "Early, SOD1 inhibitor ATN-224 has been reported to attenuate angiogenesis and tumor cell proliferation." (PMID 35978820, 2022). "We examined the GSH, SOD1, and NQO1 enzyme activity and GST levels in tumor and normal cells and found that these enzymes were at relatively higher levels in tumor tissues than in their corresponding adjacent normal tissues." (PMID 35945195, 2022). "TM has been demonstrated to inhibit angiogenesis in tumours by targeting multiple pathways including the suppression of NF-κB, HIF1α, LOX and SOD1 activities." (PMID 34604310, 2021). "The data concerning the expression and activity of SOD, SOD1, and SOD2 in blood and tumor cells are ambiguous." (PMID 34832849, 2021). "In the tumour tissues of MCF-7-xenografted BALB/c mice, Phy strongly suppressed the expression levels of Nrf2, HO-1 and SOD-1." (PMID 33715588, 2021). "We analyzed total SOD activity as well as SOD1 and SOD2 protein levels in tumor and adjacent healthy breast tissue." (PMID 29596499, 2018). "Compared with those in the normal epithelial cell line NP69 and NETs, SOD1 expression levels in a panel of NPC cells and tumour tissues respectively increased." (PMID 29891006, 2018). "Compared with the vector control-derived tumours, the tumours from 5-8F or CNE2 cells with SOD1 knockdown presented with significant growth inhibition and an increased number of apoptotic cells." (PMID 29891006, 2018). "We also observed lower levels of both SOD1 and SOD2 proteins in tumor tissue compared to adjacent healthy tissue." (PMID 29596499, 2018). "In view of the interesting divergences in the liver and tumour activity of the U. tomentosa BHE extract and its BuOH fraction, we measured the protein expression of catalase and SOD-1 in these tissues by means of Western blot." (PMID 23408945, 2013). "We have recently identified the copper-dependent enzyme superoxide dismutase 1 (SOD1) as the main target for the antiproliferative activity of ATN-224 in endothelial and tumour cells." (PMID 18253124, 2008). "In this study, we aimed to investigate whether SOD1 and SOD2 expression levels in OPC tissues influence disease progression, including primary tumor progression, lymph node metastasis, and survival prognosis." (PMID 40244057, 2025). "Upregulation of superoxide dismutase 1 (SOD1), a key enzyme for oxidative defense and downstream target of mammalian target of rapamycin complex 1 (mTORC1) is a candidate mechanism to sustain survival and proliferation of tumor cells." (PMID 39187509, 2024). "SOD1, CAT, GPX1, and HIF-1α were significantly increased in the lungs of tumour-bearing mice." (PMID 39506978, 2024). "Although the expression of SOD1 in GBs was not significantly altered, recent publications indicate a regulation of SOD1 activity by the tumor microenvironment." (PMID 39187509, 2024). "In both models, similarly to DGAT1 inhibition alone, SOD1 inhibitor treatment alone had no significant impact on tumor growth." (PMID 35732120, 2022). "Under the surviving stress upon TKIs, elevated METTL7B in LUAD cells accelerated the scavenging of excessive ROS in tumor microenvironment by upregulating the protein levels and enzymatic activities of three antioxidant enzymes GPX4, SOD1 and HMOX1 by m6A modification in their mRNAs." (PMID 35144642, 2022). "Additionally, NSCLC cells are overexpressed in SOD1 (superoxide dismutase 1), and inhibition of SOD1 kills human NSCLC cells and reduces tumor burden in mice models of NSCLC." (PMID 36358687, 2022).
tumor (continued). "Moreover, the tumor mRNA expression of glutathione S-reductase (GSR) and superoxide dismutase 1 (SOD1) showed a trend of increase, whereas catalase (CAT) was significantly downregulated." (PMID 33668151, 2021). "In conclusion, SOD1-deficient mice and tissue-specific SOD2-deficiet mice were useful model mice for an aging study without tumor progression." (PMID 33805584, 2021). "In primary cultured spleen cells transfected with Nrf2-siRNA, the WNQP failed to increase in the expression levels of Nrf2, HO-1, HO-2, and SOD-1 This suggested an important role of Nrf2 in the improvement of immune function during WNQP-mediated inhibition on tumor growth." (PMID 34307161, 2021). "Neither Sod1−/− XO-locked-type nor Sod1−/− XDH-stable-type double-mutant mice exhibited tumor formation in the liver or other tissues at 7–12 months of age (data not shown)." (PMID 33805516, 2021). "Furthermore, Phy strongly suppressed the expression levels of Nrf2 and its downstream proteins including HO-1, SOD-1 and SOD-2 in the tumour lysis of MCF-7-xenografted in BALB/c nude mice." (PMID 33715588, 2021). "SOD1, GLRX2, PRDX6, and GLRX3 genes were also overexpressed in MM patients compared to normal plasma cells, confirming that the redox status is unbalanced in tumour vs. normal cells." (PMID 33114738, 2020). "Moreover, an increase in SOD1 and ATOX1 expression has been suggested to confer cisplatin resistance to tumor cells." (PMID 32155756, 2020). "In addition, a recent study identified SOD1 as a tumor promoter in NSCLC, demonstrating that SOD1 inhibition with ATN-224 induces cellular death." (PMID 29478325, 2019). "Notably both SOD-1 and GSH blood levels were always inversely related to the tumor size and the blood ROSA levels of course." (PMID 30669508, 2019). "Moreover, the FPP® anti-tumor effect was consistent with the decrease of total ROS levels and the increase in the blood levels of GSH and SOD-1." (PMID 30669508, 2019). "While HBB is by far the most abundant transcript differentially expressed between CTCs and primary tumours, we identified 16 other antioxidant genes as being significantly upregulated, including the ALDH family members ALDH9A1 and ALDH18A1, as well as SOD1 and PRDX family members." (PMID 28181495, 2017). "Interestingly and in contrast to the ‘undead’ AiP model, removing intracellular ROS by misexpression of intracellular Catalase, SOD1 and SOD2 also strongly suppressed tumor growth." (PMID 28853394, 2017). "Long-term treatment with nelfinavir reduced protein levels of SOD1, SOD2 and catalase in tumor cells, and while it was well established that detoxifying enzymes can be activated and upregulated by ROS, their decrease in oxidative stress condition is not completely understood." (PMID 27280849, 2016). "Thus, studies aimed at exploring SOD1 as a candidate drug target in other HDR-defective gene contexts, and tumor types are highly warranted." (PMID 26318585, 2015). "Unlike in the cell model, in human tumor tissue no change in expression of the mainly cytosolic SOD1 (P00441) was observed when comparing VHL- and SDHB-derived PHEOs/PGLs." (PMID 22859959, 2012). "In fact, increased expression of SOD1, Ape1/Ref-1 and Trx in IBC could collectively help to dissipate ROS, maintain proper protein conformation and promote tumor cell survival." (PMID 20064251, 2010). "However, the mechanism of anti-tumor by regulating SOD1 signaling pathway has not been fully clarified." (PMID 37256172, 2023). "In contrast, Sod1 KO mice have been reported to reveal no tumor phenotypes until six months of age." (PMID 33805584, 2021). "Moreover, in the spleen of heterotopic tumor model BALB/c mice, ERN, LP-ERN and Tf-LP-ERN nanoparticles increased the expression levels of Nrf2, HO-1, SOD-1 and SOD-2, but reduced the expression levels of P-IKKα+β and P-NF-κB, with Tf-LP-ERN nanoparticles being most effective in this regard." (PMID 34513705, 2021).
tumor (continued). "After PPI hub genes and module analysis as well as miRNA target gene prediction, our present study preliminarily suggests downregulated ATP5H, SOD1 and upregulated EIF4G2, PABPC1 may be especially important genes involved in amorphous SiNPs-mediated tumor initiation." (PMID 30863671, 2019). "Furthermore, the capacity of SOD1 to promote angiogenesis through activation of HIF1α-mediated VEGF expression could potentially play a role in tumor progression." (PMID 20064251, 2010). "Alternatively, it is possible that SOD1 inhibition is not homogeneous throughout the tumour and that areas exist in which SOD1 inhibition is complete and direct antitumour activity may occur." (PMID 18253124, 2008). "Genes that are discriminatory in low but not high 'percentage samples' (for example, SOD1) could be expressed only at the tumour-stroma interface in stromal and/or tumour cells." (PMID 16790077, 2006). "Our data indicated that the levels of antioxidants (such as SOD1, Gpx4) in the TME of HFD-fed mice might be insufficient to protect the cells from autophagy and apoptosis during the process of tumor development, at least during the early time point after tumor implantation." (PMID 36675341, 2023). "Moreover, further analysis of the A375 tumors treated with A922500 revealed increased SESN2, SOD1, and SOD2 expression, concomitant with increased lipid peroxidation, confirming that our A922500 administration had been effective in inducing ROS and NRF2 signaling in tumor cells in vivo." (PMID 35732120, 2022). "Thus, our data only provide a rationale for studying the relationship of SOD1 inhibition to the inhibition of tumour growth in humans but may not accurately predict a correlation or lack thereof." (PMID 18253124, 2008). "It is worth noting that mRNA expression levels of other antioxidative enzymes, namely peroxiredoxin 1 (Prdx1), glutathione peroxidase (Gpx), but not superoxide dismutase 1 (Sod1), were similarly higher in the PMA type of tumor tissue than in healthy parotid tissue." (PMID 34360635, 2021).
neurodegenerative disease (244 papers, 2007 to 2026). A disorder of the central nervous system characterized by gradual and progressive loss of neural tissue and neurologic function. "ALS-increased DEGs were highly expressed by microglia and include marker genes previously linked to neurodegenerative diseases and the SOD1-G93A mouse model." (PMID 40700130, 2025). "The first gene to be identified as causative for this neurodegenerative disease was superoxide dismutase 1 (SOD1)." (PMID 40163580, 2025). "Previous studies have reported a disruption in SOD activities and mutations in SOD-1 and SOD-2, genes encoding SOD in neurodegenerative diseases." (PMID 37381025, 2023). "Canine DM is a late adult neurodegenerative disease accompanied by (SOD1) mutations (SOD1:c.118A, SOD1:c52T), and protein aggregation." (PMID 36495266, 2023). "In dogs, canine degenerative myelopathy (DM) is a neurodegenerative disease associated with aggregation of canine SOD1 (cSOD1), as occurs in ALS, and affects many dog breeds." (PMID 36615350, 2022). "Canine degenerative myelopathy (DM) is an adult-onset, chronic, progressive neurodegenerative disease caused by a DM-associated mutation (SOD1:c.118G>A, p.E40K) that commonly occurs in German Shepherd Dogs (GSDs)." (PMID 35804546, 2022). "The conformational changes of SOD1 are implicated to accelerate the aging process and also manifested in other aging-related neurodegenerative diseases like PD and AD." (PMID 35479082, 2022). "Overall, the SOD1 day 130 group had a significant increase in communities associated with neurodegenerative diseases 80,83." (PMID 33931719, 2021). "These two mutations (corresponding to c.52A > T and c.118G > A mutations in the canine SOD1 gene) are unique to canine degenerative myelopathy (DM), a neurodegenerative disease in dogs clinically and histologically similar to ALS." (PMID 32742795, 2020). "Intriguingly, despite the apparent protective role of Rac1 in neurodegenerative diseases, SOD1 mutations in microglia have been shown to enhance Rac1 activity." (PMID 27442895, 2017). "We find that a neurodegenerative disease-associated hCCS mutation abrogates the interaction with SOD1 by inhibiting hCCS zinc binding." (PMID 27282955, 2016). "ALS, a fatal degenerative disease of motor neurons, is partly caused by the mutations and aggregation of SOD1." (PMID 23755211, 2013). "Mitochondrial and redox genes such as Ucp4b and the cytochrome P450 homologs contribute to cellular oxidative homeostasis, disruption of which has been implicated in neurodegenerative disease, including SOD1 ALS." (PMID 23468938, 2013). "Many of these neurodegenerative diseases are caused by mutations in the proteinsthemselves, as with SOD1, alpha-synuclein, and the polyglutamine(polyQ) family of inherited neurological diseases, the most prominent of which is Huntington's disease." (PMID 22768276, 2012). "Furthermore, Sod1 knockout mice exhibit mild premature aging phenotypes and mutations in the Sod1 are associated with certain neurodegenerative diseases." (PMID 40690812, 2025). "Several protein groups associated with aging and neurodegenerative diseases including apolipoprotein E (ApoE), S100B, Sod1, Sod2, huntingtin (Htt), macrophage migration inhibitory factor (Mif), α-Synuclein (Snca) were modulated by either drug treatment or the behavioural training per se." (PMID 34907284, 2021). "Furthermore, we summarize novel approaches of engaging the CRISPR/Cas9 system in establishing an adequate model of neurodegenerative disease and in the treatment of SOD1-linked forms of ALS." (PMID 29562705, 2018). "Interestingly, one of the most common neurodegenerative disease among former professional soccer players is ALS whose etiology is associated with the deposition of SOD1, a metalloenzyme responsible for scavenging free radicals, into insoluble aggregates in motor neurons." (PMID 32429456, 2020).